TNF (tumor necrosis factor)
Diseases named in the same sentence as TNF in open-access papers (continued):
Sharing a sentence is not in itself a finding about the gene and the disease.
non-small cell lung carcinoma (95 papers, 2010 to 2025). A group of at least three distinct histological types of lung cancer, including non-small cell squamous cell carcinoma, adenocarcinoma, and large cell carcinoma. "The results revealed that the main pathways targeted by HPMHD for the treatment of COPD included the non-small cell carcinoma cell signaling pathway, inflammation-associated TNF signaling pathway, and IL-17 signaling pathway." (PMID 39575390, 2024). "We also found the PI3K-Akt signaling pathway, TNF signaling pathway, non-small cell lung cancer pathway, hepatitis C pathway, etc., and TNF signaling pathway genes were associated with the survival of lung adenocarcinoma." (PMID 36419898, 2022). "This process may be associated with both PI3K/AKT and TNF-α/NF-κB pathways, and sotetsuflavone may be efficacious in the treatment of non-small-cell lung cancer." (PMID 29531823, 2018). "Recent studies have found that the N,N′-disubstituted guanidino analog 1D-242 significantly inhibits RAC1-mediated TNFα-induced NF-κB nuclear translocation during non-small-cell lung cancer (NSCLC) cell proliferation and migration." (PMID 40723808, 2025). "For example, AD-MSCs have been engineered to overexpress tumor necrosis factor-related apoptosis-inducing ligand (TRAIL) and TNF-α, resulting in reduced tumor progression in non-small cell lung cancer mouse models by inducing apoptosis in cancer cells." (PMID 41332985, 2025). "In particular, long-term exposure to cisplatin, which has been reported to induce NF-κB and TNF expression in various types of cancer cells, induces ITF2 deletion in non-small cell lung cancer (NSCLC), implying an association between ITF2 and inflammation." (PMID 37185280, 2023). "Treatment for 16 individuals with advanced non-small cell lung cancer included low-dose interleukin-2 and tumor necrosis factor." (PMID 36874133, 2023). "These pathways included the TNF signalling pathway, Cytokine-cytokine receptor interaction, Osteoclast differentiation, small cell lung cancer, non-small cell lung cancer and Influenza A." (PMID 35621025, 2022). "Patients with non-small cell lung cancer were shown to have considerably higher expression levels of IL-1 and TNFα." (PMID 36133309, 2022). "A previous study focused on non-small-cell lung cancer also similarly found that CXCR5+ Tfc-like cells rapidly gained a polyfunctional effector phenotype by producing the cytokines TNF-α, IFN-γ, and IL-2 after hours of PMA/ionomycin stimulation." (PMID 35443611, 2022). "Patients with elevated TNF-α levels in islets of non-small cell lung cancer, limited primarily to macrophages and mast cells, show higher survival rates, while patients with increased TNF-α stromal content show lower survival rates." (PMID 32283655, 2020). "The recent studies demonstrated that the higher number of tumor islets with infiltration of TNFα+ TAMs (cytotoxic M1 phenotype) confers a survival advantage in non-small-cell lung cancer (NSCLC) and other malignancies." (PMID 32219066, 2020). "TRM cells in non-small cell lung cancer (NSCLC) are preloaded with preformed mRNA encoding inflammatory cytokines (granzyme B, IFN-γ, and TNF) and with cytotoxic molecules." (PMID 30100906, 2018). "Here, we report a study of the signal transduction cascades and cell-death responses induced by tumor necrosis factor alpha (TNFα) in eight human non-small cell lung cancer (NSCLC) cell lines with different levels of TNFα sensitivity." (PMID 28272488, 2017). "It has been shown that fisetin enhances the cytotoxicity of cisplatin, TNF and doxorubicin in the H1299 non-small cell lung cancer cells." (PMID 26884726, 2016). "Patients with elevated levels of TNF-α in tumor islets from non-small cell lung cancer, mainly restricted to macrophages and mast cells, showed the highest survival rates, while patients with increased stromal TNF-α content showed lower survival rates." (PMID 24901008, 2014).
non-small cell lung carcinoma (continued). "Non-small cell lung cancer has a high expression of TNF and its receptors (NSCLC)." (PMID 36874133, 2023). "In a separate study, scientists found that NSP5 caused a significantly increased expression of cytokines such as interleukin (IL)-1β, IL-6, IL-2, and tumor necrosis factor alpha (TNF-α) in a non-small-cell lung cancer cell line Calu-3 and a monocyte cell line THP1." (PMID 35682761, 2022). "Comparing with the gene ontology and KEGG analysis outcomes, genes encoding proteins targeted by ginseng leaves should play a role in PI3K–Akt pathway, MAPK signaling pathway, TNF signaling pathway, Small cell lung cancer, Non-small cell lung cancer, apoptosis." (PMID 34521875, 2021). "Both TNF and hypoxia were related to adaptive resistance of non-small cell lung cancer cells." (PMID 32923394, 2020). "One study demonstrated that the loss of TIMP3 expression might increase IL-6 production via the tumor necrosis factor α/nuclear factor κB pathway in patients with HPV-infected non-small cell lung cancer." (PMID 29731768, 2018). "Treatment with the resveratrol (10–50 μM) activated chromatin-associated SIRT1 protein on the cIAP-2 promoter region, which resulted in a loss of NF-κB-regulated gene expression and consequently augmented the tumor necrosis factor α (TNFα)-induced apoptosis in human non-small-cell lung cancer cells." (PMID 28600541, 2017). "Other groups also found that TNF-α was highly expressed in human non-small cell lung carcinoma." (PMID 27556690, 2016). "Interestingly, despite the high levels of plasma TNFα and IL-6 in patients with non-small cell lung cancer compared with healthy volunteers, the difference in plasma TNFα and IL-6 between cachectic and non-cachectic patients is not significant." (PMID 24787299, 2014). "Therefore, TNF pathway is a significant biological progression in non-small cell lung cancer." (PMID 35910766, 2022). "Furthermore, imperialine (10 mg/kg for 18 days) prominently blocked the development of non-small-cell lung cancer in the mice model, which involves the downregulation of the levels of inflammatory cytokines, such as IL-1β, IL-6, tumor necrosis factor-α (TNF-α), and the decrease of Ki67." (PMID 33273948, 2020). "This study enriched 160 pathways in total, including IL-17 signaling pathway, TNF signaling pathway, small cell lung cancer, HIF-1 signaling pathway, non-small cell lung cancer and so on." (PMID 40510163, 2025). "In non-small-cell lung cancer cells (NSCLC), TRAF2 confers resistance to TNF-mediated apoptosis and resistance to therapies." (PMID 40229245, 2025). "The expression of inflammatory markers INFγ, TNF, IL10 and PD-1 in a non-small-cell lung cancer mouse model was influenced by TERT." (PMID 39858033, 2025). "TMQ showed superior therapeutic effects to TM in non-small cell lung cancer, including an increased splenic index, IFN-γ, ROS, and MDA levels, and decreased TNF-α and IL-6 levels." (PMID 39508039, 2024). "Non-small cell lung cancer (NSCLC) cell-derived exosomal circUSP7 inhibited IFN-γ, TNF-α, granzyme-B and perforin secretion from CD8+ T cells." (PMID 38187401, 2023). "In contrast, the CD56bright subset expresses very little or no CD16 (CD56bright CD16low), produces type I pro-inflammatory cytokines IFN gamma and tumor necrosis factor (TNF) alpha, and has proangiogenic functions in non-small cell lung cancer patients." (PMID 35650630, 2022). "More recently, CD4+ CD103+ TRM cells infiltrating human non-small cell lung cancer (NSCLC) were shown to produce IFN-γ and TNF-α, resembling a TH1 phenotype." (PMID 36385379, 2022). "Tumor necrosis factor-α increases both the expression and activation of SSAT via NF-κB activation in non-small cell lung cancer cells." (PMID 36142401, 2022).
non-small cell lung carcinoma (continued). "Tumor necrosis factor (TNF) and its receptors are widely expressed in non-small cell lung cancer (NSCLC)." (PMID 33373873, 2021). "TAMs intensified hypoxia as well as oxygen glycolysis in non-small cell lung cancer (NSCLC) via AMP-activated protein kinase and peroxisome proliferator-activated receptor gamma coactivator 1-alpha, and the secretion of TNF-α." (PMID 32488850, 2020). "In non-small cell lung cancer (NSCLC), Kumar and colleagues induced EMT through dual treatment with TNFα and TGF-β." (PMID 27058560, 2016). "In primates, administration of pAg synthetic analogs and low doses of IL-2 expand Vγ9Vδ2 T cells in lung tissue, which in turn confer activity against human non-small cell lung cancer (NSCLC) cell lines by increasing the secretion of IFN-γ, TNF-α, and TRAIL." (PMID 25426120, 2014). "To examine EMT in non-small cell lung cancer (NSCLC), we utilized a three dimensional (3D) cell culture system in which cells were co-stimulated with tumor necrosis factor alpha (TNF) and transforming growth factor beta (TGFβ)." (PMID 23935876, 2013). "Non-small cell lung cancer (NSCLC) cells release circUSP7 via exosome secretion, which upregulates SHP2 expression by sponging miR-934, thereby inhibiting CD8+ T cell secretion of IFN-γ, TNF-α, granzyme B, and perforin and ultimately suppressing CD8+ T cell function." (PMID 41268548, 2025). "However, in a recent clinical study on advanced non-small cell lung carcinoma, one patient developed CRS after receiving three cycles of CAR–NK92 cells [clinicaltrials.gov ID: NCT03656705], with a reported 10-fold increase in IFN-γ and TNF-α levels." (PMID 39339180, 2024). "By contrast, pro-inflammatory Th1 cytokines including IL-2, TNF-α, IFN-γ had not noticeably altered, consistently with the study in malignant pleural effusion of non-small cell lung cancer." (PMID 37215450, 2023). "To do so, we used the A549 (non-small cell lung cancer (NSCLC)), the ACHN (renal cell carcinoma derived from pleural effusion), and the immortalized breast MCF10A cell lines treated, or not, with transforming growth factor beta (TGFβ)/tumor necrosis factor alpha (TNFα) to induce EMT6." (PMID 30814494, 2019).
acute lung injury (94 papers, 2006 to 2026). A condition of lung damage that is characterized by bilateral pulmonary infiltrates (pulmonary edema) rich in neutrophils, and in the absence of clinical heart failure. "In patients with acute lung injury, sivelestat sodium more effectively reduced IL-6, TNF-α, and CRP levels (in comparison with doxofylline), and significantly increased the oxygenation index at 24 and 72 h." (PMID 40842872, 2025). "We evaluated the levels of key cytokines, including TNF-α, IL-6, IL-1β, IL-10, IL-17, IL-22, IFN-γ, and TGF-β1, which play central roles in the inflammatory cascade associated with LPS-induced acute lung injury (ALI)." (PMID 41280422, 2025). "Kajiichigoside F1 and rosamultin were found to mitigate alveolar inflammation in mice with acute lung injury (ALI) by effectively reducing the expression of the pro-inflammatory cytokines TNF-α and IL-6." (PMID 40006066, 2025). "Elevated TNF-α levels in serum and broncho-alveolar lavage fluid of acute lung injury patients correlate with mortality rates." (PMID 36835507, 2023). "It was reported that overexpression of miR-146a suppresses the production and secretion of TNF-α, IL-6, and IL-1β to inhibit the development of LPS-induced acute lung injury." (PMID 35112981, 2022). "The treatment with Zataria multiflora (200 and 800 mg/kg) markedly reduced the WBC (total and differential) counts, serum levels of NO2, MDA, IL-17, and TNF-α as well as improved the PQ-induced acute lung injuries." (PMID 35662950, 2022). "Peritoneal injection of MOTS‐c was reported to reduce the basal levels of circulating IL‐6 and TNF‐α in mice fed with a normal diet and inhibit systemic and tissue inflammatory response in lipopolysaccharide (LPS)‐induced acute lung injury mouse model." (PMID 36156853, 2022). "DHA was previously reported to hinder the production of proinflammatory cytokines IL-1β, TNF-α, and IL-6 via regulating NF-κB signaling in acute lung injury (ALI)." (PMID 34956376, 2021). "A previous study demonstrated that thymol inhibits TNF-α and IL-6 production via the nuclear factor-kappa B (NF-κB) signaling pathway in mice with an LPS-induced acute lung injury." (PMID 31936809, 2020). "Limonin significantly decreased the levels of tumor necrosis factor-α (TNF-α), interleukin (IL-1β and IL-6), and inhibited the expression of inflammatory factors in lipopolysaccharide (LPS)-induced acute lung injury mice." (PMID 31614806, 2019). "Nilotinib was also reported to reduce IL-6, IL-1β, and TNF-α levels in mice of bleomycin-induced acute lung injury model." (PMID 31293574, 2019). "After the injury, lung epithelial secreted IL-25 promotes TNF-α production in macrophage leading to acute lung injury (ALI)." (PMID 31340864, 2019). "Several studies showed that scutellarin inhibits the expression of inflammatory cytokines, such as tumor necrosis factor (TNF)-α and IL-6, through suppressing the NF-κB pathway in LPS-activated microglia as well as in LPS-induced acute lung injury." (PMID 29375379, 2017). "XBJ was also found to inhibit IL-6 and TNF-α secretion in mice with lipopolysaccharide-induced acute lung injury (ALI) and restore the acquired immune suppression due to overactive proinflammatory cytokine productions in patients with MODS." (PMID 24369483, 2013). "Changes of circulatory parameters, including WBC number and TNF-α, in rat models of LPS-induced acute lung injury (ALI) in the earlier (6 hr after LPS), middle (12 hr after LPS), and later (24 hr after LPS) stages were examined." (PMID 23071799, 2012). "IL-10 has been shown to inhibit the production of reactive oxygen species in isolated macrophages and has been suggested to modulate TNF-α mediated, oxidative-stress- induced acute lung injury." (PMID 22978419, 2012). "Pro-inflammatory cytokines such as TNF-α, IL-6, and IL-1β, coupled with the anti-inflammatory cytokine IL-10, have important functions in the inflammatory process that leads to the advancement of acute lung injury (ALI)." (PMID 38732622, 2024).
acute lung injury (continued). "ROS drive modifications of IκB proteins, leading to their degradation and allowing active NF-κB translocation to the nucleus and inducing inflammatory cytokine release, such as (TNF)-α, IL-1β, and IL-6, which are involved in the inflammatory process of acute lung injury (ALI)." (PMID 37569801, 2023). "Besides IL-1β, tumor necrosis factor α (TNFα) is the other critical early pro-inflammatory cytokine for the development of acute lung injury and silicosis." (PMID 37864207, 2023). "In addition, nobiletin exhibited protective effects in decreasing the production of TNF-α, IL-6 via restraining activation of NF-κB signaling in the LPS-induced acute lung injury mice model and LPS-stimulated A549 cells." (PMID 36387362, 2022). "Indeed, a patent study showed that the imidazopyridine compound prevents neutrophil accumulation and TNF-α production in bronchoalveolar lavage fluids in lipopolysaccharide-induced acute lung injury mouse models." (PMID 26070068, 2015). "DA could significantly reduce the level of IL-1β, IL-6 and TNF-α in the bronchoalveolar lavage fluid of the LPS-induced acute lung injury mouse." (PMID 26223251, 2015). "In addition, TNF-α and IL-6, which are strongly induced by PFO, are involved in the development of pathological pain as well as fever, and IL-6, IL-8, and IL-10 are reported to cause acute lung injury/ARDS." (PMID 34385995, 2021). "On the other hand, Rg3 was found to decrease the levels of pro-inflammatory mediators (e.g., TNF-α and IL-1β) and increase the production of anti-inflammatory cytokines (e.g., IL-10), resulting in attenuation of damage in lipopolysaccharide-induced acute lung injury in mice." (PMID 31412594, 2019). "Furthermore, streptochlorin suppressed the infiltration of immune cells such as neutrophils into the lung and proinflammatory cytokine production such as IL-6 and TNF-α in broncho-alveolar lavage fluid (BALF) in the LPS-induced acute lung injury (ALI) mouse model." (PMID 25822875, 2015). "AS-IV decreased the levels of TNF-α, IL-6, and IL-1β in serum and BALF of mice with Acute lung injury (ALI)." (PMID 38954702, 2024). "Treatment with COST dramatically lowered IL-6 and TNF-α levels and improved lipoteichoic acid (LTA)-induced inflammatory response in an acute lung injury mouse model." (PMID 38629103, 2024). "In a mouse model of acute lung injury (ALI), Eda-Bor significantly lowered TNF-α and IL-6 levels in serum and bronchoalveolar lavage fluid and inhibited NF-κB activation." (PMID 36110124, 2022). "In acute lung injury (ALI), Met also reduces the number of inflammatory cells and expression of pro‐inflammatory cytokines such as TNF‐α, IL‐1β, and IL‐6." (PMID 34473417, 2021). "In mammals, treatment with glutamine before and after ischemia significantly attenuated the increases of TNF-α and CINC-1 levels in perfusate during ischemia-reperfusion induced acute lung injury (p < 0.05)." (PMID 35052548, 2021). "After acute lung injury (ALI), serum-derived exosomes transfer miR-155 to macrophages, activate nuclear factor κB (NF-κB), and produce tumor necrosis factor α (TNF-α) and interleukin-6, which promotes macrophage proliferation and inflammatory response." (PMID 32733944, 2020). "In animal models exhibiting LPS-induced acute lung injury (ALI), treatment with TMEE reduced the levels of macrophages influx and TNF-α production in the bronchoalveolar lavage fluid (BALF) of ALI mice." (PMID 32876073, 2020). "This study aimed to evaluate the anti-oxidative and anti-inflammatory properties of the methanol extract of SP leaves in tumor necrosis factor (TNF)-α-stimulated NCI-H292 cells and in a lipopolysaccharide (LPS)-induced acute lung injury (ALI) mouse model." (PMID 32111036, 2020). "Recently, we showed that the deletion of Apoptosis signal-regulating kinase 1 (ASK1) protects against hyperoxia-induced acute lung injury (HALI) by suppressing IL-1β and TNF-α." (PMID 27058411, 2016).